MC3R (melanocortin 3 receptor)
Description:
G protein-coupled receptor for melanocyte-stimulating hormones (alpha, beta, and gamma-MSH) and corticotropin/ACTH, which are peptide products of the POMC precursor. Upon activation, couples to G(s) protein, stimulating adenylate cyclase and the cAMP-dependent signaling pathway, which contributes to the regulation of energy homeostasis. Required for expression of anticipatory patterns of activity and wakefulness during periods of limited nutrient availability and for the normal regulation of circadian clock activity in the brain (By similarity). Binding of the Agouti-related protein/AGPR antagonist precludes alpha-MSH-induced signaling, blocking cAMP production.
Synonyms: MC3-R; MC3; BMIQ9; OB20; OQTL
Tractability: Small molecule: a high-quality ligand is known; it belongs to a druggable protein family. Antibody: its Gene Ontology location is reachable by antibodies, with high confidence; UniProt places it where antibodies can reach, with medium confidence; UniProt predicts a signal peptide or a membrane-spanning region. PROTAC: a small molecule that binds it is known. Other modalities: a drug acting on it is in phase 2 or 3 trials.
Target class: Short peptide receptor (family A GPCR); Peptide receptor (family A GPCR); Melanocortin receptor; Membrane receptor; Family A G protein-coupled receptor
Chemical probes: [D-Trp8]-γ-MSH
Gene: Protein-coding gene on chromosome 20 (56,248,732 to 56,249,815, forward strand). Ensembl gene ENSG00000124089.
Subcellular location: Cell membrane
Pathways (Reactome):
Signal Transduction: G alpha (s) signalling events; Peptide ligand-binding receptors
Developmental Biology: Transcriptional and post-translational regulation of MITF-M expression and activity
Gene Ontology:
Molecular function: corticotropin receptor activity; melanocyte-stimulating hormone receptor activity; neuropeptide binding; protein binding; melanocortin receptor activity; peptide hormone binding; G protein-coupled receptor activity
Biological process: adenylate cyclase-activating G protein-coupled receptor signaling pathway; regulation of feeding behavior; circadian regulation of gene expression; G protein-coupled receptor signaling pathway, coupled to cyclic nucleotide second messenger; phospholipase C-activating G protein-coupled receptor signaling pathway; adenylate cyclase-modulating G protein-coupled receptor signaling pathway; G protein-coupled receptor signaling pathway; homoiothermy; locomotor rhythm; neuropeptide signaling pathway; regulation of blood pressure; regulation of heart rate; sodium ion homeostasis
Cellular component: cytoplasm; plasma membrane; membrane
Genetic constraint (gnomAD): Loss-of-function variants: 12 observed, 16.25 expected, observed/expected ratio (o/e) 0.74, 90% interval 0.47 to 1.2. The upper end of that interval is the gene's LOEUF score, 1.2, which puts it in group 5 of 6, group 1 being the genes least tolerant of losing a copy. Missense variants: 432 observed, 460.06 expected, observed/expected ratio (o/e) 0.94, 90% interval 0.87 to 1.02. Synonymous variants: 174 observed, 192.42 expected, observed/expected ratio (o/e) 0.9, 90% interval 0.8 to 1.02.
Homologues: Orthologues: macaque MC3R (94% identical), dog MC3R (92% identical), rabbit MC3R (91% identical), rat Mc3r (90% identical), mouse Mc3r (89% identical), pig MC3R (86% identical), guinea pig MC3R (86% identical), tropical clawed frog mc3r (73% identical), zebrafish mc3r (70% identical). Paralogues in human: MC5R (59% identical), MC4R (57% identical), MC1R (45% identical), MC2R (42% identical), GPR12 (26% identical), LPAR1 (26% identical), S1PR2 (26% identical), GPR6 (25% identical), LPAR2 (24% identical), S1PR1 (24% identical), CNR1 (24% identical), GPR3 (24% identical), and 6 more.
Diseases named in the same sentence as MC3R in open-access papers:
MC3R is named in the same sentence as 76 diseases in open-access papers, as found by Europe PMC text mining. Sharing a sentence is not in itself a finding about the gene and the disease. The quoted sentences say what the papers report.
Obesity (71 papers, 2007 to 2026). Accumulation of substantial excess body fat. "Some studies have implicated rare heterozygous functional variants in MC3R as a contributor to early onset and/or common obesity [29,30,34,35,]." (PMID 41386534, 2026). "To determine if homozygous carriage of a loss-of-function (LoF) mutation in MC3R causes monogenic obesity in humans, we searched for further individuals homozygous for potential LoF mutations in three exome cohorts enriched for consanguinity." (PMID 41386534, 2026). "There have been many genetic studies attempting to understand the role of MC3R variants in human obesity." (PMID 41386534, 2026). "Large-scale research has also found positive associations between obesity and other gene mutations, such as MC3R and MC4R." (PMID 41596694, 2026). "Genetic polymorphisms in MC3R can impact receptor function and alter these regulatory mechanisms, potentially leading to variations in body weight and risk of obesity." (PMID 41002740, 2025). "One study, using a mature female Mc3r-null mouse model, identified a rare human loss-of-function mutation in MC3R that resulted in obesity, a decreased lean mass, and increased ovulation length." (PMID 40001512, 2025). "Given the similar obesogenic mechanism seen in our humanized MC3R mutant mouse model, insufficient peripheral activation of MC3R appears to likely play a part in explaining obesity in humans with MC3R deficiency." (PMID 39956805, 2025). "A study on the loss-of-function MC3R Ala33Thr variant pointed towards obesity-related pathways controlled by G-proteins other than Gαs, similar to MC4R." (PMID 40001512, 2025). "Genetic polymorphisms or variations in the MC3R gene can influence receptor function and have significant implications for body weight regulation and obesity." (PMID 41002740, 2025). "Mice with Mc3r deficiency develop obesity with hepatic triglyceride accumulation and disrupted hepatocellular autophagosome turnover." (PMID 39956805, 2025). "In mice, global Mc3r deficiency obesity is a mild, late-onset form of obesity, that increases body weight moderately because it increases fat mass while reducing in lean mass." (PMID 39956805, 2025). "Regardless of nutritional state, cellular mechanisms for lipid mobilization and nutrient partitioning play important roles in loss of function (LoF) MC3R-associated obesity." (PMID 39956805, 2025). "Partial/total loss of function mutations in MC3R increases three times the risk of obesity in children." (PMID 41082226, 2025). "Loss-of-function mutations in the POMC, MC4R, and MC3R genes cause severe obesity, lowering the length and quality of life of the patients due to complications such as cardiovascular disease, type 2 diabetes, and NAFLD." (PMID 40001512, 2025). "These polymorphisms can affect MC3R signaling and disrupt the normal regulation of consumption of meal and energy balance, contributing to increased susceptibility to weight gain and obesity." (PMID 41002740, 2025). "Previous studies have shown that the Mc3r–/– mouse exhibits modest, late-onset obesity, yet increased anorexia and weight loss in response to various challenges relative to WT littermates." (PMID 39007271, 2024). "In humans, rare inactivating MC3R variants have been associated with obesity, but these findings are inconsistent." (PMID 39574659, 2024). "Numerous studies have elucidated the role of the MC4R pathway and, to a lesser extent, the MC3R in the regulation of food intake and energy expenditure, with impaired signaling through these receptors being associated with obesity." (PMID 35737586, 2022). "MC3R mutations are known to cause obesity in humans, but rodent models with MC3R−/− genotype failed to exhibit the same phenotype." (PMID 31138220, 2019). "Encouragingly, the MC3R-deficient pigs developed an obese phenotype, making them a potentially very valuable model for research on human obesity." (PMID 31138220, 2019).
Obesity (continued). "Deletion of the gene encoding either MC3R or MC4R causes obesity in mice, with both affecting partitioning of nutrients between adipose and non-adipose tissues." (PMID 28360832, 2017). "Results showed that MC4R deficiency led to a dramatic alteration in energy homeostasis including obesity and hyperglycaemia, whereas MC3R deficiency showed hypophagia and reduced body weight." (PMID 27713523, 2016). "While the role of MC4R in monogenic obesity is well-defined, the role of MC3R mutations in human monogenic obesity is debated (Zegers, Beckers & Hendrickx, 2013)." (PMID 25825681, 2015). "MC3R mutations that result in defective receptors have been associated with obesity in French and Italian populations." (PMID 25825681, 2015). "In accordance with this aspect, it has been shown that the disruption of the POMC and melanocortin receptor 4 (MC4R) genes in mice models causes obesity, while MC3R gene-deficient mice have normal food consumption but accumulate fat." (PMID 25999818, 2015). "From the 23 known genes and 13 Riken transcripts; Dok5, Mc3r, Bmp7, and Pck1 have been associated with obesity." (PMID 25613955, 2015). "On the other hand, the role of the MC3R gene polymorphisms and mutations in relation to obesity is still controversial." (PMID 24142065, 2013). "Among over 20 missense substitutions in the MC3R gene two (6Thr>Val and 81Val>Ile) are common polymorphisms and one (335Ile>Ser) is considered as strongly predisposing to obesity." (PMID 24142065, 2013). "Genetic epidemiological studies have reported different results regarding the association between common MC3R variants and common forms of obesity." (PMID 21695122, 2011). "Genetic variants of MC3R have been involved in obesity development mainly in relation with its role in the control of food intake." (PMID 21695122, 2011). "Some linkage studies are concordant with the presence of a susceptibility gene for human obesity at the melanocortin-3 receptor MC3R locus (gene ID:4159; 20q13.2-13.3)." (PMID 21695122, 2011). "The consequences of MC3R mutations include severe obesity and ultradian rhythm disruptions." (PMID 40001512, 2025). "Understanding these novel mutations in POMC and MC4R/MC3R, as well as their structural and intracellular mechanisms, may help identify strategies for the treatment and diagnosis of obesity, particularly childhood obesity." (PMID 40001512, 2025). "Similarly to the binding of α-MSH to MC4R, γ-MSH binds to MC3R to regulate appetite and energy expenditure, and a loss of function of both receptors leads to severe early-onset obesity." (PMID 40001512, 2025). "Several studies have investigated the association between MC3R genetic polymorphisms and obesity." (PMID 41002740, 2025). "Another study revealed that MC3R mutations are closely associated with obesity." (PMID 31138220, 2019). "Nevertheless, the pathogenic role of MC3R in human obesity remains controversial." (PMID 31138220, 2019). "The melanocortin-3-receptor (MC3R) missense mutation Val81Ile, rs3827103, was associated with increased susceptibility to obesity and may play a role in response to weight loss intervention." (PMID 29755414, 2018). "Among the identified substitutions in the MC3R gene the 335Ile>Ser one may be considered as slightly predisposing to obesity." (PMID 24142065, 2013). "The predisposing role to human obesity of the MC3R gene polymorphism is controversial." (PMID 24142065, 2013). "Thus, deletion of MC3R in the MH increases feeding and body weight gain following more prolonged exposure to a HFD in males, suggesting that deletion of MC3R may increase susceptibility to diet‐induced obesity in a sexually dimorphic manner." (PMID 39718394, 2025). "Additionally, MC3R mutation variants cause robust obesity in humans." (PMID 38577975, 2024).
Obesity (continued). "ACP cystic fluid caused growth retardation and an increased obesity index in mice, affected the expression of the Npy, Fgfr2, Rnpc3, Sst, and Pcsk1n genes that regulate growth and energy metabolism in hypothalamic neurons, and enhanced the cellular interaction of Agrp–Mc3r." (PMID 35525962, 2022). "Additionally, some mutations in MC3R have been proposed as a cause of human monogenic obesity." (PMID 21695122, 2011). "It has been widely used to assess numerous genes associated with obesity, such as MC4R, MC3R, neuropeptide Y, leptin and its receptor." (PMID 41596694, 2026). "When the phenotypes of patients with MC3R and MC4R mutations were compared, both genes were found to be involved in severe early-onset obesity." (PMID 40001512, 2025). "The partial recovery of body weight, fat mass, and total energy expenditure at the systemic level underscores how hepatic Mc3r reactivation can modulate a systemic obesity phenotype." (PMID 39956805, 2025). "Genetic polymorphism in MC1R, MC2R, MC3R, and MC4R genes is associated with risk of melanoma, familial glucocorticoid deficiency, obesity, and type 2 diabetes mellitus, respectively." (PMID 41002740, 2025). "Our data finding Mc3rTB/TB homozygotes gain similar body weight compared to Mc4r heterozygotes confirm that Mc3r insufficiency is a moderate form of obesity that can be, to a certain extent, improved by restoring hepatic Mc3r expression." (PMID 39956805, 2025). "Loss-of-function mutations in the genes encoding POMC, MC3R, and MC4R can lead to the dysregulation of energy expenditure and feeding balance, early-onset obesity, and developmental dysregulation." (PMID 40001512, 2025). "Genes implicated in monogenic obesity include POMC, LEP, LEPR, MC3R, and MC4R, while polygenic obesity involves variants in genes such as FTO, UCP1-3, MC4R, ADRB1-3, and SLC6A14." (PMID 41302083, 2025). "The mutations in MC1R, MC2R, MC3R, and MC4R genes are associated with risk of melanoma, familial glucocorticoid deficiency, obesity, and type 2 diabetes mellitus, respectively." (PMID 41002740, 2025). "To test this, in new cohorts of mice, we fed WT littermate and MC3R floxed mice with a HFD for 6 weeks to induce obesity." (PMID 39718394, 2025). "One such example is a predicted allosteric pocket in MC3R, a new target for treatment of eating disorder and obesity." (PMID 41255992, 2025). "Six NSVs and three SVs were detected in MC3R by Sanger sequencing in study groups comprising children or adolescents with SNS or severe obesity and healthy lean controls." (PMID 37369769, 2023). "We Sanger sequenced the coding region of MC3R in 185 children or adolescents with short normal stature (SNS) or 258 individuals with severe obesity, and 192 healthy-lean individuals." (PMID 37369769, 2023). "To further investigation of the impact of variants in MC3R in the etiology of obesity and SNS, we sequenced the MC3R in children or adolescents with severe obesity and in children with SNS and healthy lean individuals as control group." (PMID 37369769, 2023). "In MC3R dysfunction, obesity presents in milder levels compared with MC4R deletion, while a coexistence of these two deficiencies has a synergic effect on increased adiposity." (PMID 36986146, 2023). "Mc3r knockout mice have moderate obesity phenotype with normal food intake and metabolism, increased fat mass, and decreased lean mass." (PMID 35204745, 2022). "In support of this, MC3R knockout mice have increased fat mass, decreased lean mass, hyperphagia, less activity, and mild late-onset obesity." (PMID 33716796, 2021). "A recent study conducted in mice shows that melanocortin 3 receptor (MC3R) regulates hepatic autophagy in obesity by possibly affecting transcription factor EB signaling." (PMID 32015340, 2020). "An HF diet exacerbates obesity in Pomc, melanocortin-3 receptor (Mc3r), or melanocortin-4 receptor (Mc4r) knockout mice." (PMID 30997487, 2019).
Obesity (continued). "While the Mc4r knockout mice exhibit marked obesity, resulting from hyperphagia and hypometabolism, genetic disruption of the Mc3r lead to a modest obesity phenotype, suggesting that MC4R constitutes the major MCR receptor involved in energy homeostasis." (PMID 28690493, 2017). "The dissociation of the effects of MC3R on obesity from altered metabolic control suggests that MC3Rs expressed by SF1(+ve) neurons in the VMH are involved in metabolic control." (PMID 28360832, 2017). "Obesity in Ay mice is believed to be a consequence of the agouti proteins serving as a constitutive antagonist of the melanocortin 3 receptor (MC3R) and melanocortin 4 receptor (MC4R) by mimicking the action of the agouti-related protein." (PMID 23418893, 2013). "There are very few studies concerning the influence of rare mutations (257Arg>Ser and 335Ile>Ser) on obesity and it seems that only the 335Ser allele may predispose to obesity, since it was shown that this variant is responsible for a disturbed ligand binding ability of the MC3R." (PMID 24142065, 2013). "Of note, the MC3R locus has not been identified as a site for common genetic variation associating with obesity, waist-hip ratio or body fat percentage." (PMID 41386534, 2026). "Finally, we applied AiPP to the entire human proteome, identifying ligandable sites in proteins that were undetected or unliganded by ABPP, including an allosteric site in MC3R, which is a therapeutic target for treatment of eating disorder and obesity." (PMID 41255992, 2025). "Thus, the structural characteristics of these protein interactions are crucial to both understanding the molecular mechanisms of MC3R and developing treatment strategies for MC3R-related obesity." (PMID 40001512, 2025). "Total activity and ambulatory activity (physical activity) were all similar between groups during both light and dark phases, suggesting that locomotion (by beam breaks) is not a contributing factor in the change in the obesity phenotype of Mc3r deficiency." (PMID 39956805, 2025). "The authors suggested that MC3R may provide a link between nutritional status and linear growth and the onset of obesity." (PMID 36943057, 2023). "Furthermore, variants in MC3R and MC4R have been shown to be closely associated with monogenic human obesity." (PMID 35204745, 2022). "Agrp combines with Mc3r to effectively promote feeding behavior and obesity." (PMID 35525962, 2022). "These forms present complete penetrance in comparison to the particular form of obesity related to MC4R, and probably MC3R as well; polymorphisms in these genes are associated with forms of obesity that are more severe than typical polygenic obesity but less severe than homozygous gene mutations." (PMID 30338250, 2018). "The MCR gene family consists of five members and two of them (MC3R and MC4R) are involved in the control of mammalian energy homeostasis and thus their mutations and polymorphisms may predispose to obesity." (PMID 24142065, 2013). "Indeed, it has been reported that mice with genetic disruption in both Mc3r and Mc4r are heavier than Mc4r−/− mice, indicating a possible non-redundant participation of both melanocortin receptors in obesity and adiposity-related phenotypes." (PMID 21695122, 2011). "Overall, the role of MC3R in feeding behaviour and obesity is less clear than for MC4R." (PMID 17764572, 2007). "Similarly one can review the evidence, either genetic or neuropharmacological, for the function of MC3R in the pathogenesis of obesity." (PMID 17764572, 2007). "The obesity of the lethal yellow and viable yellow strains of mice is due to over-expressed agouti (with AgRP-like actions) in the hypothalamus, having an antagonistic effect at the MC3R and MC4R receptor." (PMID 17764572, 2007).